CD4 (CD4 molecule)
Diseases named in the same sentence as CD4 in open-access papers (continued):
Sharing a sentence is not in itself a finding about the gene and the disease.
Hypoglycemia (3 papers, 2015 to 2023). A decreased concentration of glucose in the blood. "Thus, hypoglycemia in GHR-KO pigs might contribute to the reduced IFI44 protein abundance in CD4− PBMCs." (PMID 37189345, 2023). "Therefore, further experiments, such as functional assays investigating the substrate preferences of WT and GHR-KO PBMCs would be necessary to confirm or reject a difference in the metabolism of GHR-KO CD4+ PBMCs and possible compensatory mechanisms towards hypoglycemia." (PMID 37189345, 2023). "CD4+ and CD8+ T cell counts significantly decreased, insulin use reduced, and hypoglycemia was attenuated." (PMID 36389806, 2022). "Thus, we hypothesized that prolonged hypoglycemia and enhanced insulin sensitivity in GHR-KO pigs may lead to enhanced immune function, especially in CD4+ T cells." (PMID 37189345, 2023).
immunosuppressive disorder (3 papers, 2021 to 2025). "Other characteristics, such as ethnicity, gender of sexual partners, immunosuppressive disorder or treatment, and CD4 count, were also similar in the two groups." (PMID 40573925, 2025). "Disseminated KS is frequently seen in HIV population with low CD4 + cells count or HIV-uninfected patients with other immunosuppressive disorders as transplant recipients." (PMID 34930492, 2021).
intestinal cancer (3 papers, 2019 to 2024). "We first found that the expression of three genes regulated by these miRNAs was significantly correlated with the survival time of intestinal cancer, and then found that CD4 memory resting cells, macrophages." (PMID 37465677, 2023). "Nevertheless, our data indicate that ST2+ CD4+ FOXP3+ Tregs may also promote tumorigenesis in other murine models of CRC based on genetic ablation of tumor suppressor genes critically regulating intestinal cancer." (PMID 31165767, 2019).
intestinal schistosomiasis (3 papers, 2011 to 2018). An intestinal infection that is caused by Schistosoma japonicum. "As cytokine environments, especially those of CD4+ helper T cells, play important roles in the generation of hepatic granulomatous lesions in intestinal schistosomiasis, the cytokine profiles of the hepatic CD4+ T cells were analyzed." (PMID 24358216, 2013). "Furthermore, HIV binding receptors (CCR5 and CXC4) are denser on CD4 T-cell surfaces in men with intestinal schistosomiasis compared to uninfected individuals and those treated with praziquantel." (PMID 30543654, 2018). "Thus, our study implicates CD4+CD25+FoxP3+Tregs as a source of regulatory pressure during chronic intestinal schistosomiasis and in the wider context, as suppressors of Th2-driven pathology in the colon." (PMID 21858239, 2011).
keratoconjunctivitis (3 papers, 2011 to 2018). Inflammation of both the cornea and the conjunctiva. "Two of the patients initially not taking highly active antiretroviral therapy (HAART) and presenting with an absolute CD4+ T cell count less than 100 cells/μL had a more severe form of keratoconjunctivitis than the third patient (receiving HAART, with a CD4+ T cell count of 259 cells/μL)." (PMID 21559864, 2011). "In patients with keratoconjunctivitis (KCS), hypersensitive and inflammatory cytokines, such as IL-17 and IFN-γ, are secreted from the resident intraepithelial lymphocytes and infiltrating CD4+ T cells due to desiccation in the tear film of the ocular surface." (PMID 30002412, 2018).
kidney toxicity (3 papers, 2015 to 2023). "In our study, older patients and those with lower baseline eGFR, lower CD4 count, lower body weight and concomitant protease inhibitor use were at increased risk of kidney toxicity, which concurs with previous studies." (PMID 28406595, 2017). "The association between nephrotoxicity and 10-week mortality remained significant following adjustment for the baseline creatinine level, weight, CD4 count, fungal burden, altered mental status, and study (10-week aOR, 4.5; 95% CI, 1.8 to 11; P = 0.001)." (PMID 26349818, 2015). "Children on TDF+3 TC + EFV, those with CD4 count of <200 cells/mm3 and with renal toxicity were at 4.10 (95%CI = 1.64, 6.89), 2.16(95%CI = 1.31, 4.26) and 5.94 (95%CI = 1.18, 29.89) times risk of vitamin-D in-sufficiency, respectively." (PMID 37215860, 2023).
Kimura disease (3 papers, 2016 to 2023). "Kimura disease is suspected to be an IgE-mediated disease, associated with an allergic response, in which antigen-specific B cells are stimulated to undergo specific IgE class switching with disease-specific CD4+ T (Th) cells help." (PMID 31852109, 2019). "One study investigated the CD4+ T cells in the salivary glands of IgG4-RD patients and Kimura disease patients." (PMID 37762039, 2023).
Klebsiella pneumonia (3 papers, 2013 to 2023). An pneumonia caused by infection with Klebsiella. "In fact, a previous report noted that a significant fraction of lung CD4+IL17+ TRM cells were derived from IL-17A-producing effector (Th17) cells following immunization with heat-killed Klebsiella pneumonia." (PMID 38093320, 2023). "In order to determine the naive CD4+ T cell stimulatory capacity of purified respiratory DC subsets activated by Klebsiella pneumonia we used an in vitro model system with CFSE-labelled OVA TCR transgenic CD4+ T helper cells as antigen-specific responder cells." (PMID 24044871, 2013). "The functional CD4+ naive T cell stimulatory capacity of purified respiratory DC subsets was determined in vitro after Klebsiella pneumonia lysate stimulation of ovalbumin-pulsed DCs and ovalbumin (OVA) T-cell receptor (TCR)-transgenic naive CD4+ responder T cells." (PMID 24044871, 2013). "In direct comparison to other respiratory DC subsets, Klebsiella pneumonia-stimulated CD103+ DC and CD11b DC represented the most efficient naïve CD4+ T cell activators." (PMID 24044871, 2013). "Interestingly, sorted DC subsets that were not activated with Klebsiella pneumonia induced comparable CD4+ T cell proliferation indicating that Klebsiella may induce both activatory and inhibitory effects on DC." (PMID 24044871, 2013).
Klinefelter syndrome (3 papers, 2019 to 2023). A sex chromosome disorder caused by the presence of an extra X chromosome in the male karyotype. "In detail, immunoglobulin concentrations, CD4+T cell numbers, CD4/CD8 T cell ratios, and B cell numbers of patients with Klinefelter syndrome (XXY syndrome) were higher than XY male." (PMID 35783087, 2022). "Identification of significant differences in chromosome X organization among human female healthy and SLE CD4+ T lymphocytes may provide a new and much-needed non-symptomatic diagnostic marker for SLE in women and men with Klinefelter syndrome." (PMID 31142749, 2019).
Legionella infection (3 papers, 2012 to 2024). "Moreover, individuals with this immune profile had a 5% higher risk of ICU admission, even after controlling for potential confounders such as Legionella infection, viral load, CD4 count, and TB coinfection (crude RR 1.021 [CI 1.011–1.031] vs. adjusted RR 1.047 [CI 1.027–1.066])." (PMID 38392911, 2024). "MAIT cell protection is more evident in mice lacking CD4+ cells, and adoptive transfer of MAIT cells rescues immunodeficient Rag2−/−γC−/− mice from lethal Legionella infection." (PMID 30135490, 2018).
Lipoatrophy (3 papers, 2011 to 2025). Localized loss of fat tissue. "Fear of developing lipoatrophy may cause caregivers to become non-adherent with ART, leading to loss of CD4 cells, subsequent opportunistic infection and possibly death." (PMID 23176441, 2012). "Overall, children with and without lipoatrophy had similar weight-for-age Z-score, height-for-age Z-score, gender distribution, ethnic distribution, WHO clinical stage, viral load and mean CD4." (PMID 23176441, 2012).
lymphangiectasia (3 papers, 2020 to 2024). "Conversely, in the course of IBD, abnormal lymphocyte function in peripheric circulation and at the intestinal mucosal level, due to the loss of CD4+ T cells and lymphangiectasia, can occur." (PMID 38539935, 2024). "Genital oedema and likelihood of concomitant intestinal lymphangiectasia independently predicted CD4+ T cell depletion." (PMID 38022535, 2023). "Furthermore, increasing likelihood of intestinal lymphangiectasia had a significant trend with reduced CD4 count." (PMID 38022535, 2023).
malignant mesothelioma (3 papers, 2015 to 2024). A malignant neoplasm of the pleura or peritoneum, arising from mesothelial cells. "Immune cells with a high degree of infiltration in malignant mesothelioma tissues included CD4+T memory dormancy cells, CD4+T memory activation cells, macrophage M0, macrophage M1, and macrophage M2." (PMID 37139482, 2023). "Moreover, we demonstrate that tumor-specific cytotoxic CD8+ T cells, but neither CD4+ T cells nor antibodies, confer the protection, suggesting that CD8+ T cells may play a central role in antigen spreading-mediated immunotherapeutic efficacy against malignant mesothelioma in mice." (PMID 26431275, 2015).
malignant pleural mesothelioma (3 papers, 2018 to 2023). A malignant neoplasm that arises from mesothelial cells in the pleura and shows a diffuse growth pattern. "Finally, regarding peripheral T cells from healthy donors (HD) and asbestos-exposed patients with pleural plaque (PP) or malignant pleural mesothelioma (MPM), following stimulation of CD4+ T cells, T cells from MPM patients showed reduced potential of interferon (IFN)-γ expression." (PMID 29419731, 2018).
marasmus (3 papers, 2006 to 2023). The lack of sufficient energy or protein to meet the body's metabolic demands, as a result of either an inadequate dietary intake of protein, intake of poor quality dietary protein, increased demands due to disease, or increased nutrient losses. "Several studies have reported that HIV-infected children tend to develop marasmus rather than kwashiorkor and that CD4 count remains higher in HIV-infected children with kwashiorkor compared to those with marasmus." (PMID 18671876, 2008).
mastocytoma (3 papers, 2014 to 2024). A localized tumor composed of sheets of mast cells without atypia. "In our colleagues’ study, freshly isolated murine CD4+T cells were incubated with murine mastocytoma P815 cells transfectants expressing a similar level of either CD80 or CD86 in the presence of anti-CD3 mAb." (PMID 25344652, 2014). "For conjugate formation with CD4+ T cells and CTL, the mouse mastocytoma cell line P815 was used to generate stimulatory cells." (PMID 38166948, 2024).
mastocytosis (3 papers, 2013 to 2016). A clonal myeloproliferative neoplasm characterized by the proliferation and accumulation of neoplastic mast cells in one or multiple organs or organ systems. "Taken together this suggests that CD4+ T-cells drive a cascade in which I-cell hyperplasia produces hypophagia and weight loss, lowering pro-inflammatory leptin levels which feed back to influence the protective Th2 immune response, augmenting mastocytosis and allowing parasite expulsion." (PMID 23349631, 2013). "(iii) In the amplification-of-mastocytosis phase, repeated food antigen ingestion induces the increase of CD4+TH2 cells, which provide the IL-4 signaling that induces MC progenitors to develop into MMC9s, which expand greatly after ingested antigens cross-link with MMC9 surface IgE/FcεR complex." (PMID 27853507, 2016).
mediastinal lymphoma (3 papers, 2020 to 2025). "The availability of information on the CD4+/CD8+ ratio in cats with mediastinal lymphoma that have been treated using chemotherapy is inadequate due to limited studies." (PMID 35158547, 2022). "The CD4+/CD8+ ratio during the induction phase of COP chemotherapy in cats with mediastinal lymphoma was not different from pretreatment, though it can cause changes in the WBC, neutrophils, PCV, and MCV." (PMID 35158547, 2022). "The objective of this study was to evaluate the effect of the COP chemotherapeutic protocol on hematological parameters, CD4+/CD8+ ratio, and the mortality of 18 client-owned FeLV-infected cats with mediastinal lymphoma." (PMID 35158547, 2022). "The objectives of this study were to evaluate the effect of the COP chemotherapeutic protocol on hematological parameters, the CD4+/CD8+ ratio, and mortality in FeLV positive cats with mediastinal lymphoma." (PMID 35158547, 2022).
multinodular goiter (3 papers, 2014 to 2025). Nodular goiter characterized by more than one discrete tissue mass. "The percentage of CD4+CD25+CD127low/- Treg among CD4+ T cells was significantly more elevated in PTC patients than in multinodular goiter (MNG) patients." (PMID 31500315, 2019).
multiple system atrophy (3 papers, 2020 to 2021). Multiple system atrophy (MSA) is a neurodegenerative disorder characterized by autonomic failure (cardiovascular and/or urinary), parkinsonism, cerebellar impairment and corticospinal signs with a median survival of 6-9 years. "Similarly, in the substantia nigra of cases with multiple system atrophy compared to controls both CD4+ and CD8+ T lymphocytes were found to be increased." (PMID 33272323, 2020). "Patients were followed up at 0, 1, 3, and 6 months after treatment, and the Unified Multiple System Atrophy Rating Scale (UMSARS) scores, TNF-α in the peripheral blood, IL-6, percentage of CD4, and CD4/CD8 ratio were evaluated and compared for each follow-up point; any adverse effects were recorded." (PMID 34900026, 2021).
Myelodysplasia (3 papers, 2018 to 2023). Clonal hematopoietic stem cell disorders characterized by dysplasia (ineffective production) in one or more hematopoietic cell lineages, leading to anemia and cytopenia. "The normal ratio of CD4/CD8 is ≥1.8, and an inverted ratio (i.e., <1) has traditionally been associated with immune senescence, myelodysplasia, and persistent viral infections such as HIV (Human immunodeficiency virus), HCMV (Human cytomegalovirus), and EBV (Epstein–Barr virus)." (PMID 37762135, 2023). "In myelodysplasia patients treated with DAC, IFNγ expression by CD4+ T cells was not promoted." (PMID 29850630, 2018).
necrotizing enterocolitis (3 papers, 2016 to 2022). Necrotizing enterocolitis (NEC) is a devastating disease that affects mostly the intestine of premature infants. "CD4+ T cells have been co-cultured with brain organoids to study the effects of necrotizing enterocolitis in the brain." (PMID 34832665, 2021). "Moreover, even CD4 + T cells in the intestine of necrotizing enterocolitis (NEC, necrotizing enterocolitis) mice induce NEC-associated brain injury by releasing IFN-γ in brain organoids via blood circulation." (PMID 36523428, 2022).
neuritis (3 papers, 2017 to 2024). A neuropathy arising from inflammation of one or more nerves. "It suggests that P2X7R in CD4+ T cells may play an important role in mediating neuritis pathogenesis in EAN." (PMID 38528529, 2024). "Interestingly, this neuritis is CD4+ T cell-dependent featuring enhanced production of pro-inflammatory IL-17 without any alternation in Treg numbers." (PMID 29179723, 2017). "However, 2D2xCD19-BMHCIIxIgHMOG mice were completely resistant to both optic nerve inflammation and spontaneous EAE despite a substantial reconstitution of the CD4 T cell compartment with MOG-specific T cells as reported." (PMID 29944721, 2018).
NK cell leukemia (3 papers, 2020 to 2025). "In fact, they are regarded as the signature of an aggressive clinical course with a poor prognosis in CD8+ T-LGLL and aggressive NK cell leukemia, while they are devoid of negative prognostic significance in CD4+ T-LGLL and Tγδ LGLL." (PMID 32133291, 2020). "In fact, it is regarded as the signature of an aggressive clinical course with a poor prognosis in CD8+ TLGLL, characterized by CD56+/CD16–/CD57– LGLs, and aggressive NK cell leukemia, while it is devoid of negative prognostic significance in CD4+ T-LGLL and Tγδ LGLL." (PMID 32133291, 2020).
oligoarticular JIA (3 papers, 2009 to 2022). "Since the CD4:CD8 ratio is a simple laboratory measure that can be routinely applied, we considered its merit as a predictive test for the likelihood of extension of oligoarticular JIA." (PMID 20127724, 2010).
opioid use disorder (3 papers, 2023 to 2024). A substance-related disorder that involves the recurring use of opioids despite negative consequences. "Other drugs such as opioid use disorders may have similar effects on gut permeability and microbial translocation, resulting in B cell perturbations, anti-CD4 IgG production, and blunted CD4+ T cell reconstitution, which deserves further investigations." (PMID 37027536, 2023).
ovarian insufficiency (3 papers, 2021 to 2024). "Changes in T-cell subsets and T-cell-mediated immune impairment in patients with early ovarian insufficiency are indicated by decrease of CD4 + T cells, increment of CD8 + T cells, and reduction of CD4+/CD8 + ratio." (PMID 38877588, 2024). "After 5 weeks, Rag1−/‐ mice transferred with CD4+CD25−CD45RBhi T cells exhibited the ovarian insufficiency phenotype, with smaller ovarian size and decreased number of follicles in different stages (POI group)." (PMID 34185428, 2021).
ovarian serous carcinoma (3 papers, 2013 to 2023). "Aim: to analyze mRNA expression of EGFL7 within the tumor microenvironment of high-grade ovarian serous carcinoma and its association with a number of intraepithelial CD4+/CD8+ lymphocytes and ICAM-1 expression." (PMID 35630004, 2022). "We performed immunofluorescence and quantification of intraepithelial tumor-infiltrating triple positive Tregs (CD4+CD25+FOXP3+), as well as CD4+CD25+FOXP3-, CD3+ and CD8+ T cells in tumor specimens from 52 patients with high stage serous ovarian carcinoma." (PMID 24244610, 2013).
pancreatic neuroendocrine tumor (3 papers, 2019 to 2024). Pancreatic endocrine tumor, also known as pancreatic neuroendocrine tumor (PNET), describes a group of endocrine tumors originating in the pancreas that are usually indolent and benign, but may have the potential to be malignant. "Likely, elevated stromal CD4+ T cell level in pancreatic neuroendocrine tumor correlated with shorter recurrence-free survival." (PMID 37215452, 2023). "T cell depletion using anti-CD4 and -CD8 antibodies were also shown to reduce the number of TA-HEVs in murine pancreatic neuroendocrine tumors." (PMID 38812785, 2024).
papillary renal cell carcinoma (3 papers, 2021 to 2025). A rare subtype of renal cell carcinoma, arising from the renal tubular epithelium and showing a papillary growth pattern, which typically manifests with hematuria, flank pain, palpable abdominal mass or nonspecific symptoms, such as fatigue, weight loss or fever. "BUB1B expression is positively related to the infiltration of CD4 + T cells and macrophages in papillary renal cell carcinoma." (PMID 41163302, 2025). "Alphataxin was shown here to effectively elevate CD4+ T cell numbers and CD4/CD8 T cell ratios both in circulation and within tumors in non-tumor bearing mice and in two orthotopic renal adenocarcinoma mouse studies." (PMID 34900690, 2021).
peritoneal cancer (3 papers, 2016 to 2024). A peritoneum cancer that is located in the inside of the abdomen. "In preclinical models, IL-33 delays metastatic progression of peritoneal cancer via induction of an allergic tumor microenvironment in which eosinophils, CD4+ T cells, and macrophages contribute to anti-tumoral effects." (PMID 37064719, 2023).
plasmacytoma (3 papers, 2016 to 2022). Plasmacytoma is a localized mass of neoplastic monoclonal plasma cells that represents approximately 5% of all plasma cell neoplasms. "Elimination of the MHC negative plasmacytoma MOPC315 involves indirect recognition by CD4+ T cells of tumor antigen presented by infiltrating macrophages, followed by differentiation of cytotoxic macrophages through direct contact with the T cells." (PMID 30190583, 2018).
Pleuritis (3 papers, 2008 to 2011). Inflammation of the pleura. "Further, we confirm that low CD4 cell count could also be found in HIV negative TB pleuritis patients." (PMID 18366633, 2008).